MYCN (MYCN proto-oncogene, bHLH transcription factor)
Diseases named in the same sentence as MYCN in open-access papers (continued):
Sharing a sentence is not in itself a finding about the gene and the disease.
neuroblastoma (continued). "Indeed, a major direct mitogen of hepatocytes, the epidermal growth factor (EGF), stimulated MYCN gene expression in neuroblastoma cells via the recruitment of the transcription factor Sp1 to the MYCN promoter region." (PMID 33937011, 2020). "The data collectively demonstrated that RNA m6A modification was required for miR-98/MYCN axis-mediated inhibition of neuroblastoma progression, and miR-98 might be novel targets for NB detection and treatment." (PMID 32788584, 2020). "Suppression of let‐7 family miRNA expression in neuroblastoma cells overexpressing LIN28B increases MYCN expression, resulting in elevated MYCN protein levels in high‐risk neuroblastomas, including those that lack MYCN amplification." (PMID 32945147, 2020). "MYCN amplification was strongly correlated with a poor prognosis in neuroblastoma cases." (PMID 32963529, 2020). "High-risk MYCN non-amplified neuroblastoma often have an increased Wnt activity which contributes to its high aggressiveness by inducing c-MYC expression." (PMID 33585251, 2020). "Few studies have reported MYCN‐amplification status in neuroblastoma cases diagnosed in individuals with congenital overgrowth syndromes, but the possible connection between this specific subtype and these syndromic conditions requires further study to guide screening and targeted therapy." (PMID 32945147, 2020). "Therefore, YG1702 has potential as a therapeutic drug that induces ACD and reduces the malignant transformation of MYCN-amplified neuroblastoma cells." (PMID 33194665, 2020). "The intersection of the most differentially overexpressed genes in tumors with the highest MYCN expression and genes predicted to be located in the plasma membrane resulted in 14 potential cell-surface targets in MYCN amplified neuroblastoma tumors, 11 of which have TSS-proximal E-boxes." (PMID 32211329, 2020). "Furthermore, TBX2 acts as a neuroblastoma core regulatory circuitry component that promotes MYCN/FOXM1-mediated reactivation of DREAM targets, while CLOCK genes are closely associated with cancer development, particularly in endocrine tissues." (PMID 32391054, 2020). "MYCN amplification is a major determinant of poor disease outcome in neuroblastoma." (PMID 32131402, 2020). "We previously reported that miR-506-3p repressed MYCN expression in neuroblastoma cells." (PMID 32087738, 2020). "More importantly, MYCN has been confirmed to be a drug target in MYCN-amplified neuroblastoma." (PMID 32857725, 2020). "To determine whether ATRX mutations and MYCN amplification are incompatible in vivo, we conditionally inactivated ATRX in two genetically engineered neuroblastoma mouse models 8,17,18." (PMID 32060267, 2020). "In a panel of neuroblastoma cell lines, MYCN amplification or MYCN expression resulted in increased cell death in response to a range of PARP inhibitors (niraparib, veliparib, talazoparib and olaparib) compared to the response seen in non-expressing/amplified cells." (PMID 32577161, 2020). "Interestingly, a compelling study revealed a positive correlation between ABCC1 and MYCN in neuroblastoma patients exhibiting MYCN amplification as well as in neuroblastoma cells engineered to overexpress the protein." (PMID 32718079, 2020). "In the MYCN-amplified neuroblastoma progression, MYCN is detected in circulating DNA." (PMID 32849827, 2020). "The molecular etiology of neuroblastoma has been intensively studied at the level of deregulated transcriptomes resulting from altered developmental transcription factor expression, as exemplified by MYCN." (PMID 32210188, 2020). "This may relate to the fact that tumour cells, including MYCN-amplified neuroblastoma cells, harbour elevated levels of GSH to compensate for, and defend against, higher ROS production." (PMID 33028860, 2020).
neuroblastoma (continued). "Conversely, MYCN has been shown to induce MDM2 expression in neuroblastoma cells, yet it is unclear if MYC shares this ability, if MYC family proteins upregulate MDM2 in other malignancies, and if this regulation occurs during tumorigenesis as well as in cancer cell lines." (PMID 33425720, 2020). "HSP90 inhibition revealed a novel therapeutic mechanism of antitumor activity in MYCN-amplified neuroblastoma cells that may enhance therapeutic sensitivity." (PMID 33569349, 2020). "PIPs have also shown effectiveness in targeting genetic aberrations other than single-base mutations, such as the case with copy-amplified MYCN, an aberration in neuroblastoma, where appreciable DNA damage and induced apoptosis were observable in MYCN-amplified neuroblastoma mouse models." (PMID 32260120, 2020). "MYCN was first reported in 1983 as an amplified gene homologous to v-myc in human neuroblastoma." (PMID 33628735, 2020). "DP-GMM analysis of the 44 enriched GO term genes identified three MYCN-NA neuroblastoma clusters." (PMID 32275708, 2020). "However, we demonstrated for the first time that combined glutamine deprivation with radiation therapy in MYCN-amplified neuroblastoma led to an increase in radioresistant cells that is associated with upregulation of c-Myc expression in these cells." (PMID 32483461, 2020). "As tumor cells may often be unavailable, we developed a method to detect MYCN amplification in the plasma of patients with neuroblastoma." (PMID 32896084, 2020). "Due to the epigenetic modulation, these agents offer an effective means to therapeutically alter the regulation of proto-oncogenes and tumor suppressor genes in malignant cells and induce pro-apoptotic transcriptional changes in MYCN amplified neuroblastoma cell lines." (PMID 32971811, 2020). "We also analyzed the prognostic effects of MYCN target genes in pediatric neuroblastoma." (PMID 32593299, 2020). "We here investigated the effects of ectopic MYCN expression in neuroblastoma cells lines in the presence of high or low supply with glucose or glutamine, respectively, as an approach to mimic both, oncogene-induced changes in metabolic patterns and response to altered carbon source supply." (PMID 32346009, 2020). "To evaluate the clinical relevance of PLAGL2 in neuroblastoma patients, we examined the correlation of PLAGL2 mRNA expression with MYCN mRNA levels in neuroblastoma patients as well as its correlation with patient survival based on published neuroblastoma patient datasets." (PMID 32087738, 2020). "The tumors were phenotypically and molecularly similar to human MYCN-amplified neuroblastoma." (PMID 33585251, 2020). "The MYCN oncogene is amplified in approximately 20% of neuroblastomas (NBs)." (PMID 33381457, 2020). "Recent studies show that high N-MYC protein and RNA levels could be better biomarkers than MYCN gene amplification in predicting the prognosis of neuroblastoma patients, underscoring the importance of aberrant expression of N-MYC in tumor progression." (PMID 33614505, 2020). "However, the overlaps between different prognostic signatures were limited and results from MYCN silencing in neuroblastoma IMR32 cell line demonstrated a completely different prognostic signature." (PMID 32593299, 2020). "MYCN plays an important role in neuroblastoma pathogenesis, and it was discovered that TAp73α could interact with and destabilize MYCN mRNA in glioblastoma cells." (PMID 33375680, 2020). "Furthermore, the expression of Aurora-A is increased in the MYCN-amplified neuroblastoma, suggesting a potential feed-forward loop that improves the stability of both proteins." (PMID 33614505, 2020). "The high affinity of pralatrexate for the SLC19A1 encoded RFC-1 protein may demonstrate a potential role in the treatment of MYCN-amplified neuroblastoma." (PMID 32850011, 2020).
neuroblastoma (continued). "Lastly, there are some latent biological factors beyond those available in SEER that are known to affect survival in neuroblastoma patients and may be potentially confounded with race, such as MYCN, ploidy, and tumor histology, among others." (PMID 32679868, 2020). "MYCN amplification drives one in six cases of neuroblastoma." (PMID 33199677, 2020). "We therefore conclude that chimeric co-amplification of proto-oncogenes partly explains the malignant phenotype of neuroblastomas with complex MYCN amplicons, whereas enhancer hijacking in class II amplicons does not change clinical behavior, fully phenocopying class I MYCN amplicons." (PMID 33199677, 2020). "Importantly, the HAUSP inhibitor P22077 markedly suppresses the growth of MYCN-amplified human neuroblastoma cell lines in xenograft mouse models." (PMID 33628735, 2020). "Because the stabilization of MYCN is a critical function of AURKA in human neuroblastoma, we want to validate whether the inhibition of AURKA induces MYCN degradation in our study." (PMID 31920463, 2020). "These PNA analogs of different length were tested in the “miRNA-34a–MYCN” axis, being the MYCN oncogene a validated target of tumor suppressive miRNA-34a in different cancers, including Neuroblastoma." (PMID 33330358, 2020). "Moreover, our results demonstrated an up-regulation of ALDH1A3 and downregulation of CD44 proteins upon glutamine starvation in MYCN-amplified neuroblastoma cells, while a downregulation of both CSC markers was observed in SH-SY5Y cells." (PMID 32483461, 2020). "Importantly, PARP inhibition caused a significant increase in the survival of mice bearing MYCN expressing tumours in a transgenic murine model of MYCN expressing neuroblastoma." (PMID 32577161, 2020). "MP1 is a novel marinopyrrole analogue with activity in MYCN amplified neuroblastoma cell lines." (PMID 33322110, 2020). "MYCN amplicons are either organized as extrachromosomal double minutes or as homogeneously stained regions in addition to the single copy of MYCN on the short arm of chromosome 2, retained at 2p24, in neuroblastoma cells and other solid tumor cells." (PMID 33937011, 2020). "Significant positive correlation between PLAGL2 and MYCN mRNA levels were observed in all three datasets, suggesting that the positive regulatory loop formed between PLAGL2 and MYCN play a critical role in controlling the expression of each other in neuroblastoma tumors." (PMID 32087738, 2020). "Since the major function of MYCN is as a transcription factor, further studies are needed to clarify whether HMGA1, a target of MYCN, is involved in the cell division fate of human neuroblastoma cells." (PMID 33194665, 2020). "Similarly, loss of nf1 function accelerates disease onset and increases the penetrance of MYCN-induced neuroblastoma in Tg(dbh:GFP-MYCN) transgenic zebrafish." (PMID 32759814, 2020). "Finally, the membrane localization of CAMKV was confirmed in MYCN amplified NGP neuroblastoma cells by immunofluorescence." (PMID 32211329, 2020). "Neuroblastoma is a heterogeneous disease which displays common genomic aberrations, such as deletion of parts of chromosome arms 1p and 11q, gain of 17q, and amplification of the MYCN oncogene." (PMID 31334113, 2019). "For the two human neuroblastoma tissues with unknown MYCN amplification status, 17q/JMJD6 gene was gained in both of the samples." (PMID 31346162, 2019). "The major marker attributed to high-risk neuroblastoma is MYCN gene amplification and high-risk neuroblastoma patients without MYCN-amplification frequently exhibit high expression of either MycN, c-Myc, or Myc signature genes." (PMID 30542116, 2019). "Signaling via the PI3K/Akt pathway in neuroblastoma regulates the phosphorylation of MYCN through GSK3b and mTOR, which makes this pathway a suitable candidate for pharmacological inhibition in order to indirectly target MYCN stability." (PMID 35582571, 2019).
neuroblastoma (continued). "Although there is no reported correlation between MYCN and DHA, the existing evidence suggests that both MYCN and DHA associate with neuroblastoma initiation and development, and the relationship between these two factors should be comprehensively elucidated to develop novel treatments." (PMID 31856871, 2019). "Approximately 20% of primary neuroblastoma tumors demonstrate MYCN amplification." (PMID 30754710, 2019). "In this study, we used the non-MYCN-amplified or overexpressed neuroblastoma cell line SK-N-SH." (PMID 30741995, 2019). "Overall, we found that downregulation of 7 genes (Crb1, Lrrc9, Rcn1, Rtl1, Shisa3, Six6, St18) and upregulation of 2 genes (C1ql3, Slc18A1), are strongly predictive of favorable neuroblastoma outcome, consistent with delayed tumor development in Th-MYCN/Casp2−/− mice." (PMID 30670683, 2019). "The FBXW7 E3-ubiquitin ligase is an important regulator of MycN stability in neuroblastoma cells." (PMID 30542116, 2019). "Overall, we boldly speculate that PRPS1 is closely related with MYCN to regulate cell proliferation in neuroblastoma." (PMID 31443513, 2019). "PRMT1 siRNA knockdown reduces MYCN expression and neuroblastoma cell viability." (PMID 30741995, 2019). "Furthermore, overexpression of MYCN in primary neural crest cells result in neuroblastoma formation when these cells are transduced back into mice." (PMID 30760980, 2019). "However, the relationship between survivin expression and MYCN amplification and stage of neuroblastomas requires further analysis." (PMID 30609639, 2019). "ELOVL2 Knockdown showed the opposite effect in MYCN single-copy neuroblastoma cells." (PMID 31856871, 2019). "In the laboratory, many mono-or pan-CDK inhibitors have been reported to display robust anti-tumor effects either by down-regulating MYCN protein or shutting down its transcriptional activity in neuroblastoma (THZ1, CYC065 and dinaciclib) or other cancers (SY-1365, BAY1143572)." (PMID 35582571, 2019). "The overexpression of MYCN contributes to the genesis of neuroblastoma in the transgenic mice." (PMID 31396265, 2019). "Pediatric neuroblastoma can have two different molecular phenotypes: tumors with amplified MYCN oncogene, deemed to be of high-risk clinically, or tumors without MYCN amplification which have a relatively better prognosis." (PMID 31828566, 2019). "Interestingly, in vitro or in vivo treatment of MYCN-amplified and therapy-resistant neuroblastoma cells with antagomir-17-5p led to inhibition of growth of these cancer cells through activation of apoptosis." (PMID 30713602, 2019). "It is unclear whether MYCN is involved in chromatin remodeling in neuroblastoma through regulation of its target genes." (PMID 31396265, 2019). "Among 107 high risk neuroblastoma patients enrolled in this study, 106 were stage M or metastatic high risk patients and 1 was stage L2 non-metastatic high risk patients with MYCN amplification." (PMID 31619207, 2019). "To test whether this function of MYC is conserved for its different isoforms, we repeated the 4sU sequencing experiment in SH-EP neuroblastoma cells that express a MYCN-estrogen receptor chimeric protein." (PMID 30928206, 2019). "Furthermore, the previously reported 51 MYC target genes in neuroblastoma tumors were significantly down-regulated as MYCN knockdown." (PMID 31396265, 2019). "5-hmC profiling could provide information on factors that determine the clinical behavior of neuroblastoma: MYCN status, copy-number alterations, and transcriptional networks, using one simple assay." (PMID 31179414, 2019). "Aurora-A kinase inhibitors have been shown to effectively target MYCN amplified neuroblastoma by destabilizing N-Myc expression, which is also the basis for exploring Aurora-A kinase inhibitors for the treatment of NEPC or N-Myc overexpressed CRPC (clinical trial #NCT01799278)." (PMID 30657058, 2019). "Inhibition of MYCN down-regulated FACT expression in neuroblastoma cells, and vice versa." (PMID 31396265, 2019).
neuroblastoma (continued). "Moreover, amplification of MYCN mRNA levels in neuroblastoma can sponge Let-7, thereby rendering LIN28B dispensable for cancer progression." (PMID 31354514, 2019). "In conclusion, establishing MYCN downstream signaling pathways in neuroblastoma may improve our capacity in identifying molecular interactions, disease pathways, and even targeted drug discovery." (PMID 31624245, 2019). "In conclusion, our study indicated that loss of α-N-catenin exists in a subgroup of neuroblastoma and correlates with relapse-free survival in patients lacking MYCN amplification." (PMID 31489113, 2019). "Based on the SEER database, it was found that stage 4 disease, unfavorable DNA ploidy, MYCN gene amplification decreased the 5-year survival rates, while age, tumor location, stage are independent prognostic factors for neuroblastoma." (PMID 31338261, 2019). "In neuroblastoma, lorlatinib has demonstrated promising results as a single agent in various pre-clinical models, being able to overcome crizotinib resistance and showing dramatic inhibition of tumor growth of neuroblastoma xenografts or MYCN and ALKF1174L driven tumors in a transgenic mouse model." (PMID 31452835, 2019). "Variables with prognostic significance in patients with neuroblastoma, including age at diagnosis, disease stage, tumor histology, MYCN gene amplification, tumor cell ploidy, and the presence of segmental chromosomal aberrations are utilized to classify patients based on risk of disease recurrence." (PMID 30626019, 2019). "In line with the inhibitory effects observed on N‐Myc protein levels following IBL‐302 treatment, PIM/PI3K targeting might have a stronger effect against MYCN‐amplified neuroblastoma as compared to non‐MYCN‐amplified tumors." (PMID 31310053, 2019). "Besides ASCL1, we found that the receptor tyrosine kinase gene RET was positively regulated by LMO1 and MYCN in neuroblastoma cells." (PMID 31819055, 2019). "Integrating anti-MYCN ChIP-seq and gene expression profiles of neuroblastoma patients revealed the metabolic enzymes, MTHFD2 and PAICS, required for one-carbon metabolism and purine biosynthesis were concomitantly upregulated, which were more susceptible to metastatic neuroblastoma." (PMID 31624245, 2019). "Together, these data identify altered expression levels of several Wnt-associated genes and suggest a fine-tuning of Wnt signaling components in Th-MYCN/Casp2−/− tumors that may determine neural crest cell (NCC) specification to influence neuroblastoma onset." (PMID 30670683, 2019). "Upon depletion or inhibition of MRE11 by knockdown or use of mirin, the accumulation of replication stress and DNA damage can be induced and results in significant impairment of tumor growth in vivo, suggesting the potential role of MRE11 inhibition in treating MYCN-amplified neuroblastoma." (PMID 31767017, 2019). "MAPK inhibition blocks sphere formation in MYCN-amplified neuroblastoma cell lines." (PMID 31191243, 2019). "Also, ectopic expression of MYCN in the neural crest of zebrafish results in neuroblastoma development." (PMID 30760980, 2019). "In the INRG schema, non-high-risk neuroblastoma patients include those with localized disease, all L1 tumors and L2 tumors without MYCN gene amplification." (PMID 30626019, 2019). "5-hmC profiling could provide information on factors that determine the clinical behavior of neuroblastoma (ie, MYCN status, copy number alterations, and transcriptional networks) using one simple assay." (PMID 31179414, 2019). "Furthermore, combining the compound perturbagens to MYCN target gene pair displayed synergistic effects in MNA neuroblastoma cells which provides therapeutic opportunities for children with neuroblastoma." (PMID 31624245, 2019). "In this study, we investigated whether cisplatin treatment triggers TRAIL‐mediated cytotoxicity in TRAIL‐resistant IMR‐32 neuroblastoma cells which exhibit amplification of MYCN oncogene and lack caspase‐8 expression." (PMID 30724400, 2019).